BNAT1 (breast cancer associated ESR1 regulating natural antisense transcript 1)
Synonyms: LL21NC02-21A1.1
Gene: Long non-coding RNA gene on chromosome 21 (45,403,809 to 45,404,943, reverse strand). Ensembl gene ENSG00000273796.
Diseases named in the same sentence as BNAT1 in open-access papers:
BNAT1 is named in the same sentence as 2 diseases in open-access papers, as found by Europe PMC text mining. Sharing a sentence is not in itself a finding about the gene and the disease. The quoted sentences say what the papers report.
breast carcinoma (1 paper, 2022). "We consider that BNAT1 could be a potential molecular target for diagnostic and therapeutic options targeting luminal-type and endocrine-resistant breast cancer." (PMID 36429038, 2022). "We next investigated whether BNAT1 is expressed in ER-positive clinical breast cancers and whether it is associated with the prognoses of patients." (PMID 36429038, 2022). "In clinicopathological study, BNAT1 may have clinical relevance as a potential diagnostic factor for prognoses of ER-positive breast cancer patients based on an in situ hybridization study for breast cancer specimens." (PMID 36429038, 2022). "We next assessed the relationship between BNAT1 positivity and the clinical prognosis of breast cancer patients." (PMID 36429038, 2022). "We examined BNAT1 expression in 115 clinical breast cancer specimens that were excised from patients as primary breast cancer tissues and previously defined as ER-positive by an immunohistochemical study." (PMID 36429038, 2022). "In this study, we performed RNA-sequencing for ER-positive breast cancer cells and identified a novel estrogen-inducible antisense RNA in the COL18A1 promoter region, named breast cancer natural antisense transcript 1 (BNAT1)." (PMID 36429038, 2022). "Microarray analysis revealed that BNAT1 silencing in estrogen-sensitive breast cancer cells repressed estrogen signaling." (PMID 36429038, 2022). "BNAT1 silencing inhibited in vitro and in vivo growth of endocrine-resistant breast cancer cells by repressing ERα expression and signaling." (PMID 36429038, 2022). "We designated the E2-inducible lncRNA identified in this region as “breast cancer natural antisense transcript 1”, or BNAT1." (PMID 36429038, 2022). "In situ hybridization analysis showed that BNAT1 positivity in ER-positive breast cancer tissues was significantly correlated with poorer patient prognosis in comparison to BNAT1 negativity." (PMID 36429038, 2022). "Further studies may define the role of BNAT1 in differential chromosomal interactions in ER-positive endocrine-resistant breast cancer cells." (PMID 36429038, 2022). "While BNAT1 is located on chromosome 21, questions may arise as to whether other ESR1-modulating factors on different chromosomes including TMPO-AS1 and Eleanors contribute to the expression of BNAT1 in breast cancer cells." (PMID 36429038, 2022). "BNAT1-specific siRNAs could reduce the in vivo tumor formation derived from tamoxifen-resistant breast cancer cells." (PMID 36429038, 2022). "The present study defines that BNAT1 is a pivotal estrogen-inducible lncRNA that could activate ERα signaling and promote breast cancer tumorigenesis." (PMID 36429038, 2022). "BNAT1 includes a functional ERα binding site in its RNA sequence and its expression is upregulated in tamoxifen-resistant MCF7 breast cancer cells compared with parental MCF7 cells." (PMID 36429038, 2022).
tumor (1 paper, 2022). "In the OHTR-derived xenograft model, the intratumoral injection of BNAT1-specific siRNA significantly repressed in vivo tumor growth." (PMID 36429038, 2022). "Overall, BNAT1 is a functional lncRNA that regulates ERα transcriptional activity and contributes to estrogen-dependent cell proliferation and tumor formation in ER-positive breast cancer." (PMID 36429038, 2022). "The administration of siRNAs specific to BNAT1 could reduce the in vivo tumor growth of OHTR-derived xenografts, thus exhibiting their therapeutic effects on endocrine-resistant breast cancer." (PMID 36429038, 2022). "The correlation between BNAT1 positivity and overall survival was not determined because no patients with a BNAT1-negative tumor died during the observation period." (PMID 36429038, 2022).